ZNF91 (zinc finger protein 91)
Description:
Transcription factor specifically required to repress SINE-VNTR-Alu (SVA) retrotransposons: recognizes and binds SVA sequences and represses their expression by recruiting a repressive complex containing TRIM28/KAP1. May also bind the promoter of the FCGR2B gene, leading to repress its expression; however, additional evidence is required to confirm this result in vivo.
Synonyms: HPF7; HTF10
Tractability: PROTAC: ubiquitination databases record sites on it.
Gene: Protein-coding gene on chromosome 19 (23,304,991 to 23,395,501, reverse strand). Ensembl gene ENSG00000167232.
Subcellular location: Nucleus
Gene Ontology:
Molecular function: DNA-binding transcription repressor activity, RNA polymerase II-specific; DNA-binding transcription factor activity; transcription cis-regulatory region binding; zinc ion binding
Biological process: transposable element silencing; regulation of transcription by RNA polymerase II; negative regulation of transcription by RNA polymerase II; regulation of DNA-templated transcription
Cellular component: nucleus
Genetic constraint (gnomAD): Loss-of-function variants: 5 observed, 9.21 expected, observed/expected ratio (o/e) 0.54, 90% interval 0.28 to 1.14. That is too few expected variants to judge how well the gene tolerates losing a copy. Missense variants: 1,158 observed, 1,307 expected, observed/expected ratio (o/e) 0.89, 90% interval 0.84 to 0.93. Synonymous variants: 437 observed, 433.02 expected, observed/expected ratio (o/e) 1.01, 90% interval 0.93 to 1.09.
Homologues: Orthologues: macaque ZNF91 (65% identical), zebrafish znf646 (17% identical), zebrafish si:dkey-89b17.4 (17% identical), Drosophila melanogaster zf30C (16% identical), Drosophila melanogaster CG18011 (15% identical), zebrafish znf576.1 (14% identical), Drosophila melanogaster CG6791 (13% identical), Drosophila melanogaster CG30020 (12% identical), Drosophila melanogaster hang (11% identical), Caenorhabditis elegans ztf-15 (11% identical), Drosophila melanogaster CG1602 (10% identical), Drosophila melanogaster az2 (10% identical), and 20 more. Paralogues in human: ZNF208 (56% identical), ZNF729 (52% identical), ZNF99 (50% identical), ZNF107 (49% identical), ZNF160 (35% identical), ZNF420 (33% identical), ZNF347 (32% identical), ZNF184 (31% identical), ZNF845 (30% identical), ZNF84 (30% identical), ZNF594 (29% identical), ZNF665 (28% identical), and 24 more.
Diseases named in the same sentence as ZNF91 in open-access papers:
ZNF91 is named in the same sentence as 20 diseases in open-access papers, as found by Europe PMC text mining. Sharing a sentence is not in itself a finding about the gene and the disease. The quoted sentences say what the papers report.
colon cancer (3 papers, 2016 to 2024). "In UC GRN analysis, ZNF91 regulates 397 UC common overregulated DEGs, which are known to be co-expressed in colon cancer, related to transmembrane transport, mitochondrial function, and multiple metabolic pathways and diseases." (PMID 39791702, 2024). "ZNF91 is another key regulator according to UC GRN, along with 44 other TFs, and regulates 397 UC common overregulated DEGs, co-expressed in colon cancer and related to transmembrane transport, mitochondrial function, and multiple metabolic pathways and diseases." (PMID 39791702, 2024).
colorectal cancer (3 papers, 2023 to 2024). A primary or metastatic malignant neoplasm that affects the colon or rectum. "ZNF91 mutation was the one of eight predictors for colorectal cancer and was observed in 14.9% of patients." (PMID 37726835, 2023). "ZNF91 is related to poor prognoses of esophageal cancer patients, to AML cell proliferation and anti-apoptosis, to irradiation resistance by regulating the stem cell-like properties of NSCLC cells, and to the occurrence and development of colorectal cancer." (PMID 39791702, 2024).
esophageal cancer (2 papers, 2023 to 2024). A primary or metastatic malignant neoplasm involving the esophagus. "Results indicate that ZNF91, and ZNF586 were upregulated in esophageal cancer tissue than adjacent tissue, whereas ZNF502, ZNF865, ZNF106, and ZNF225 was downregulated." (PMID 37013470, 2023).
microcephaly (2 papers, 2023). A congenital or acquired developmental disorder in which the circumference of the head is smaller than normal for the person's age and sex. "Human-specific SVAs in microcephaly CDK5RAP2 and epilepsy SCN8A gene introns repress their expression via transcription factor ZNF91 to delay neuronal maturation." (PMID 36997626, 2023). "Over-expressing SVA-lncRNA AK057321 or deleting ZNF91, each independently, increases CDK5RAP2 gene expression, a microcephaly gene with an intronic human-specific SVA_F that increases during neuronal maturation." (PMID 36997626, 2023).
Vertigo (2 papers, 2021 to 2022). An abnormal sensation of spinning while the body is actually stationary. "The vertigo association with the sequence variants at ZNF91, OTOP1, and OTOGL appears to be driven by their risk of BPPV." (PMID 34620984, 2021). "Variants in OTOG and otogelin like (OTOGL), otopetrin 1 (OTOP1), tectorin α (TECTA), zinc finger protein 91 (ZNF91), and armadillo repeat containing 9 (ARMC9) were associated with vertigo in a recent genome-wide meta-analysis." (PMID 35741759, 2022).
Crohn disease (1 paper, 2024). A gastrointestinal disorder characterized by chronic inflammation involving all layers of the intestinal wall, noncaseating granulomas affecting the intestinal wall and regional lymph nodes, and transmural fibrosis. "ZNF91 and TP53TG1 in Crohn’s disease are related to the regulation of PPAR, MAPK, and metabolic signaling pathways." (PMID 39791702, 2024).
endometrial cancer (1 paper, 2025). Primary or metastatic malignant neoplasm involving the endometrium (mucous membrane that lines the endometrial cavity). "For instance, nude mice are used to examine the role of circ-ZNF91 in vivo; endometrial cancer cells with interfering RNA for circ-ZNF91 are used to be transplanted into nude mice and the development of tumors." (PMID 41299798, 2025). "In endometrial cancer tissues, circ-ZNF91 shows a negative correlation with the expression of miRNA-23B and miRNA-122A2, suggesting that this circRNA may act as a miRNA sponge to inhibit the expression of miRNA-23B and miRNA-122A2 in cells." (PMID 41299798, 2025).
hepatocellular carcinoma (1 paper, 2023). A malignant tumor that arises from hepatocytes. "Previous studies have found that ZFP91 (Zinc finger protein 91) can be a tumor suppressor for liver cancer occurrence and metabolic reprogramming, which can be a potential new prognostic biomarker and HCC (Hepatocellular Carcinoma) treatment target." (PMID 38110999, 2023).
pancreatic cancer (1 paper, 2021). "Zinc finger protein 91 (ZFP91), a novel E3 ubiquitin ligase, is demonstrated to be upregulated in prostate cancer, colon cancer and pancreatic cancer." (PMID 33755268, 2021).
prostate carcinoma (1 paper, 2023). A carcinoma that arises from epithelial cells of the prostate gland. "Comparing the mutations in pre- and post- resistant samples, we also fund that MUC7 and MUC5B mutation repair may be associated with longer PFS and ZNF91 mutation may be a key factor contributing to the development of drug resistance in prostate cancer." (PMID 37726835, 2023).
ulcerative colitis (1 paper, 2024). An inflammatory bowel disease involving the mucosal surface of the large intestine and rectum. "ZNF91, VDR, DLEU1, SATB2-AS1, and TP53TG1 in ulcerative colitis are related to the regulation of PPAR, AMPK, and metabolic signaling pathways." (PMID 39791702, 2024).
cancer (3 papers, 2015 to 2022). A tumor composed of atypical neoplastic, often pleomorphic cells that invade other tissues. "Circ_ZNF91, which is carried in exosomes from hypoxic cancer cells, can be taken up by normoxic cancer cells, leading to gemcitabine resistance and glycolysis." (PMID 35055115, 2022). "Despite the generally low PSI values for the 325 cryptic 3’SSs from the CLL-only analysis, we identified four genes previously implicated in cancer (TTI1, MAP3K7, FXYD5, PFDN5) and six others (YIF1A, ORAI2, ZNF91, ZNF548, RP11–1280I22." (PMID 25768983, 2015). "A potential role has been suggested for ZNF91 in some cancer pathogenesis and zinc finger proteins may play a role attenuating the cellular effects of viral genes that may account for some 15% of cancer." (PMID 30598658, 2018).
ZNF91 also shares sentences with these, for which no sentence is quoted: ovarian carcinoma (2 papers); tumor (2); bladder cancer (1); cardiac hypertrophy (1); epilepsy (1); gastrointestinal stromal tumor (1); lung adenocarcinoma (1); nephrotic syndrome (1).